PPARG (peroxisome proliferator activated receptor gamma)
Diseases named in the same sentence as PPARG in open-access papers (continued):
Sharing a sentence is not in itself a finding about the gene and the disease.
lipodystrophy (continued). "TZD use was associated with improved A1c in aggregated lipodystrophy (least square mean reduction 2.2%) and in PPARG-related but not LMNA-related partial lipodystrophy (Level 4 evidence)." (PMID 37794082, 2023). "This demonstrates that hyperosteoclastogenesis is not intrinsically linked to PPARγ deficiency, but is a consequence of the total lipodystrophy." (PMID 33869176, 2021). "PPARγ agonists have been proposed to be promising candidate drugs in the treatment of HIV-1 brain inflammation and neurocognitive outcomes, especially as they are already being used in treatment of HIV-associated lipodystrophy." (PMID 34445581, 2021). "PPARγ is necessary for adipogenesis; mice lacking PPARγ and humans with dominant negative mutations in PPARγ have severe lipodystrophy and are insulin-resistant." (PMID 33050467, 2020). "Taken together, these results indicate that PPARγ agonist treatment improved several metabolic disorders independently of adipose tissue function in aKO mice, suggesting that HMGCR-mediated lipodystrophy was minimally associated with the deficiency of MVA-derivative PPARγ ligands." (PMID 30396151, 2018). "Besides, recent studies indicate PPARγ play an important role in antiretroviral treatment related adipocyte dysfunction and lipodystrophy in HIV-infected patients." (PMID 30186237, 2018). "SREBP1 and PPARγ have an established role in FA biosynthesis and adipocyte differentiation, are subjected to transcriptional coactivation by PGC-1α, and their impairment has been directly associated to congenital forms of lipodystrophy." (PMID 28986436, 2017). "Therefore, PPARG has a central role in mammalian adipogenesis, typified by PPARG LOF in humans, which is associated with severe lipodystrophy, and metabolic dysfunction and disease." (PMID 28588550, 2017). "Inherited lipodystrophies include BSCL (Berardinelli–Seip congenital lipodystrophy) type 1–4, familial partial lipodystrophy associated with mutations in PPARγ (peroxisome proliferator-activated receptor gamma) and other genes, Mandibuloacral dysplasia-type A lipodystrophy and-type B lipodystrophy." (PMID 25195639, 2014). "Both HIV and antiretroviral therapy (ART, specifically the protease inhibitor and nucleoside reverse transcriptase inhibitor classes of agents) may modulate lipodystrophy via down-regulation of partial peroxisome proliferator-activated receptor-gamma (PPAR-γ)." (PMID 23516440, 2013). "First, we were not able to search for another mutations linked to lipodystrophy phenotypes (PPARG, AKT2, and PLIN1)." (PMID 22938045, 2012). "PPARγ is known to exhibit preferential expression in subcutaneous adipose tissue and has been associated with genetic forms of lipodystrophy where PPARγ genes were absent." (PMID 20573187, 2010). "Since PPARγ is playing a central role in adipose tissuedifferentiation and function, decreased PPARγ expression could be expected to be involved inthe pathophysiology of lipodystrophy." (PMID 19125203, 2009). "When PPARG null embryos are provided with a wild-typeplacenta, this cardiac defect was corrected permitting delivery, althoughpostnatal pathologies (including multiple haemorrhages and lipodystrophy)resulted in lethality." (PMID 18309368, 2008). "Those so-called open conformations also could not explain known lipodystrophy mutations in PPARγ, where the PPARγ-RXRα crystallographic complex provide an excellent explanation based on the observed DBD-LBD interactions of the closed structure." (PMID 37732120, 2023). "Therefore, to examine whether lipodystrophy in aKO mice resulted from a reduction of PPARγ activity, we next orally administered a synthetic PPARγ agonist (pioglitazone [Pio], 30 mg/kg/day) to the mice for 10 weeks." (PMID 30396151, 2018).
lipodystrophy (continued). "PIs and NRTIs, the twomajor classes of antiretrovirals associated with lipodystrophy in HIV-infected patients,may interfere at several steps of PPARγ signaling in adipose cells, such asdifferentiation, insulin action, oxidative stress, inflammation, andmitochondrial function." (PMID 19125203, 2009). "HIV-1 infection-mediated interference of PPARγ-dependent pathways in adipocytes and other cells inside adipose depots such as macrophages is likely to create an altered local environment that, after antiretroviral treatment, leads to lipodystrophy in HIV-1-infected and HAART-treated patients." (PMID 19081837, 2009). "Whether this mutation alone could have caused overt lipodystrophy in this patient could not be established, despite the clear association between PPARG and fat metabolism, and it was suggested that a second genetic defect could be required to express the lipodystrophic phenotype." (PMID 37569420, 2023). "In contrast, Pparγ2 KO mice, which lack PPARγ exclusively in the WAT, developed severe lipodystrophy, remained insulin-resistant throughout life, and died significantly earlier than controls." (PMID 33799894, 2021). "In contrast, another lipodystrophy model MORE-PGKO, which is a generalized PPARγ knockout mouse, were hypotensive." (PMID 34409079, 2021). "Human lipodystrophies used to be rare but HIV lipodystrophy, strongly associated with the earlier HIV antiviral drugs, has been common in subjects treated for HIV; again the molecular mechanisms involved are not clearly understood but may involve disturbances of adipocyte PPARγ and GLUT4 activity." (PMID 25688231, 2015). "In fact, in thissame sense, it has been observed that PPARγ expression is lower in HIV-1-infected and HAART-treatedpatients with lipodystrophy relative to healthy controls, but similar whencompared to levels in antiretroviral-naive patients." (PMID 19081837, 2009). "Metreleptin use is associated with the lowering of triglycerides and haemoglobin A1c (HbA1c) in all lipodystrophy (n = 111), partial (n = 71) and generalised lipodystrophy (n = 41), and in LMNA, PPARG, AGPAT2 or BSCL2 subgroups (n = 72,13,21 and 21 respectively)." (PMID 37794082, 2023). "BMI was lower after treatment in aggregated lipodystrophy, in generalized and partial subgroups, and in those with LMNA or BSCL2 mutations, but not PPARG or AGPAT2 mutations (Level 3 evidence)." (PMID 37794082, 2023). "The fact that E379 and R212 residues are located in predicted, but functionally elusive interaction interfaces of PPARγ:RXR and PPARγ:DNA, respectively, prompted us to study the transcriptional and epigenomic effects of the E379K and R212Q lipodystrophy mutants in detail." (PMID 36402763, 2022). "In vivo, patients with lipodystrophyhad lower adipose tissue expression of both PPARδ and PPARγ than those without lipodystrophy." (PMID 19325916, 2009). "Moreover, considering that blocking of the ALK7 signals upregulates the adipose master regulators, C/EBPα and PPARγ, it should not induce unlimited lipolysis resulting in lipodystrophy." (PMID 36626233, 2023). "PPARγ hypomorphic mice (PPARγhyp/hyp) presented neonatal mortality; the surviving animals exhibited a lipodystrophy, with moderate glucose intolerance but not a fatty liver, and compensatory regulation of genes in the muscle that allowed the oxidation of lipid excess." (PMID 32351670, 2020). "Mouse full body PPARγ KO MORE-PG does not mimic the human lipodystrophy findings." (PMID 27483259, 2016). "It appears therefore that lowered PPARγ activity, regardless of its origin, may be common to multiple types of lipodystrophy." (PMID 18752661, 2008). "Serum triglyceride concentration decreased in aggregated lipodystrophy and in those with LMNA-related but not PPARG-related partial lipodystrophy (Level 4 evidence)." (PMID 37794082, 2023).
bladder cancer (119 papers, 2005 to 2026). "This strategy identified a large module of Luminal TFs, including known Luminal-associated TFs (e.g., FOXA1/GATA3/PPARG), as well as TFs with yet unexplored roles in Luminal bladder cancer biology (e.g., HES1, FOXQ1, ZBTB7C, MECOM, GRHL2/3, and TBX3)." (PMID 36944729, 2023). "Epithelial membrane protein 1 (EMP1) deficiency promotes bladder cancer cell migration and confers resistance to ferroptosis/oxidative stress, thereby promoting bladder cancer metastasis via PPARG." (PMID 36077637, 2022). "Accordingly, in a different subtype of bladder cancer, muscle-invasive bladder cancer, recurrent mutations in RXRα lead to an imbalance of the PPARγ/RXRα heterodimer, and focal amplification of PPARγ." (PMID 35954274, 2022). "PPARG agonists have profound effects on urothelial differentiation and PPARG mutations and amplifications contribute significantly to bladder cancers." (PMID 34697317, 2021). "In the absence of ligands, PPARγ Q286E that was a mutation found in patients with bladder cancer induced a constitutively active conformation of PPARγ and promoted coactivator recruitment, providing evidence for tumorigenic effects." (PMID 33266062, 2020). "Some recurrent PPARG mutations in luminal bladder cancer increase the ligand-independent transcriptional activity of PPARγ, resulting in the upregulation of PPARγ target genes." (PMID 33266062, 2020). "In a similar way, the PPARγ Q286E mutation in our study elicited transactivation regardless of ligand binding, thus supporting the pro-tumorigenic effects of PPARγ gain-of-function mutations in bladder cancer." (PMID 33266062, 2020). "In the literature some evidence is present in relation to RXRα and PPARγ genes mutations in bladder cancer that can cause PPARs/RXRα pathway hyperactivation resulting in the cellular proliferation, even though they were not related to ATRA treatments." (PMID 32756427, 2020). "It has recently been suggested that activation of the PPARγ/RXRα pathway via mutations in PPARG or RXRA promotes tumorigenesis in luminal bladder cancer." (PMID 33266062, 2020). "More importantly, the PPARγ agonist pioglitazone was shown to be associated with an increased risk of bladder cancer." (PMID 30845932, 2019). "Activation of the PPARγ/RXRα pathway in luminal bladder cancers has mainly been linked to PPARG gene amplifications and activating point mutations in RXRα." (PMID 30651555, 2019). "Recent genomic analysis suggested potential risk of bladder cancer upon activation of PPARγ signaling pathway." (PMID 30845932, 2019). "In MIBC cohort and human bladder cancer cell lines, the expression of PPARG and its target genes were found inversely associated with the activation of PI3K-Akt pathway." (PMID 30845932, 2019). "In the present study, we investigated the association of PPARγ expression with the prognosis of patients from bladder cancer cohorts." (PMID 30845932, 2019). "A meta-analysis found a modest but clinically significant increase in overall risk of bladder cancer upon long term treatment of another PPARγ agonist Pioglitazone." (PMID 30486822, 2018). "Prolonged and higher PPARγ activity levels are associated with higher incidences of bladder cancer, potentially due to the downstream effects of PPARγ-mediated metabolism." (PMID 28348577, 2017). "On the other hand, the relationship between the use of insulin sensitizing peroxisome proliferator-activated receptor gamma agonists for the treatment of type II DM, such as pioglitazone, and the risk of bladder cancer is still under debate." (PMID 25874217, 2015). "Recently, the US Food and Drug Administration released safety information linking pioglitazone, which targets PPARγ, to increased risk for bladder cancer." (PMID 24203162, 2014). "The high incidence of prostate and bladder carcinoma poses a significant health risk for men, including Australian and North American males Interestingly, the expression of PPARγ is increased with grade and advancement of disease." (PMID 16519808, 2006).
bladder cancer (continued). "Higher levels of PPARG are associated with late-stage and more aggressive bladder cancer." (PMID 37666817, 2023). "Moreover, we investigated the underlying mechanism of SNHG1 in the bladder cancer process via miR-9-3p/MDM2/PPARγ axis." (PMID 36230661, 2022). "PPARG mutations and genomic alterations are common in bladder cancer." (PMID 34697317, 2021). "However, the PPARγ Q286E mutation found in bladder cancer increased PPARγ transactivation by inducing the active conformation, favoring the recruitment of RXRα and co-activators without ligand binding." (PMID 33266062, 2020). "Indeed, several recurrent PPARγ mutations in luminal bladder cancer have been shown to induce the hyperactivation of PPARγ in a ligand-independent manner." (PMID 33266062, 2020). "In aggregate, PPARγ plays a crucial role in driving cell biology and it is emerging as a promising therapeutic target; however, inconsistent conclusions highlight the urgent need to decipher the underlying mechanism for the diverse characters of PPARγ in modulating bladder cancer." (PMID 30845932, 2019). "In aggregate, these data suggests that the inhibition of Akt signaling pathway might serve as an important mechanism underlying the suppression of bladder cancer by PPARγ activation." (PMID 30845932, 2019). "Use of the PPARγ agonist pioglitazone has been also suspended in France and Germany due to concerns it may increase one's risk of bladder cancer." (PMID 29181019, 2017). "The mechanism of PP5 expression and tumorigenesis has yet to be determined, but it may potentially regulate PPARγ in the bladder epithelium similar to adipose, as high levels of PPARγ are also associated with bladder cancer." (PMID 28348577, 2017). "Thus, GW9662 had no inhibitory effect on ciglitazone-mediated cell death; and yet it was efficient since it inhibited overexpression of the A-FABP PPARγ target when it was associated with ciglitazone in T24 bladder cancer cells as already described." (PMID 29296202, 2017). "In addition to incidence rates, PPARγ activity is associated with increased bladder cancer cell migration and invasion." (PMID 28348577, 2017). "Taken together, we hypothesized bladder cancer was linked with fatty acid and lipid metabolism via PPARγ signalling pathway." (PMID 27779188, 2016). "Additionally, pioglitazone, a peroxisome proliferator-activated receptor gamma (PPAR-γ) agonist, has been associated with an elevated bladder cancer risk, prompting caution in clinical guidelines, yet exhibits promising effects in cancers of the breast, lung, and colon." (PMID 39595655, 2024). "However, in bladder cancer, studies have shown that PPARγ signaling could enhance the risk of developing bladder cancer, and promote the progression and metastasis of bladder cancer via providing a tumor-promoting microenvironment." (PMID 35418978, 2022). "Moreover, PPARγ agonists have also been associated with an increased incidence of subcutaneous sarcomas and elevated risk of bladder cancer, and tumor promotion may rely on PPARγ activation." (PMID 33995008, 2021). "The current medications available, thiazolidinediones (TZDs), are PPARγ full agonists associated with dangerous side effects including hepatotoxicity, increased risk for cardiovascular failure, myocardial infarction, increased risk for bladder cancer, and body weight gain." (PMID 32308671, 2020). "Male-specific hub genes, including DAXX, IKBKB, PDGFRA, and PPARG, showed significant correlations with immune cell types, highlighting a distinct immune microenvironment in male bladder cancer." (PMID 40458476, 2025). "The MEK/ERK pathway inhibits PPARG transcriptional activity and promotes its degradation through phosphorylation—a mechanism particularly active in BASQ bladder cancer and central to PPARG downregulation in this subtype." (PMID 41438986, 2025). "PPARγ activation can promote bladder cancer by enhancing cell proliferation, survival, and migration." (PMID 40290121, 2025).
bladder cancer (continued). "Covalent PPARγ inverse agonists are currently being developed as potential therapeutics in bladder cancer where hyperactivation of PPARγ transcription occurs." (PMID 40021712, 2025). "The significant positive correlations between PPARG and monocytes and activated mast cells in both genders highlight its potential role in shaping the immune landscape in bladder cancer." (PMID 40458476, 2025). "Supporting this, public datasets show that inhibition or knockout of PPARG in bladder carcinoma cells significantly reduces SCD expression." (PMID 41383134, 2025). "The study showed that bergenin can hinder the advancement of bladder cancer by activating the PPARγ/PTEN/AKT signaling pathway." (PMID 39834829, 2024). "Bergenin, one of the active ingredients of AGS, had been found to inhibit bladder cancer progression by activating the PPARγ/PTEN/Akt signal pathway." (PMID 36624500, 2023). "Using this system, we performed a genome-wide CRISPR knockout screen that generated a robust dataset valuable to the study of PPARγ and bladder cancer biology." (PMID 37250326, 2023). "Functional validation of the dataset confirmed GATA3, SPT6, and the cohesin complex components SMC1A, and RAD21, as permissive upstream positive regulators of PPARG gene expression in luminal bladder cancer." (PMID 37250326, 2023). "In order to study the regulation of PPARG gene expression in bladder cancer, we developed a cell-based reporter system that reflected endogenous changes in PPARG expression." (PMID 37250326, 2023). "Previous work showed that the three master Luminal TFs (FOXA1, GATA3, and PPARG) had to be perturbed simultaneously to induce a cell identity switch from luminal to basal in bladder cancer cell lines." (PMID 36944729, 2023). "The major aim of the study was to identify potential regulators of PPARG gene expression in bladder cancer and to generate a publicly available resource to drive and support future studies." (PMID 37250326, 2023). "PPARγ is required for normal differentiation of the urothelium and is thought to be an essential driver of the luminal subtype of bladder cancer." (PMID 37250326, 2023). "Results from TCGA samples revealed that the expression of PPARG was augmented in patients with early stage bladder cancer and was attenuated in those with more advanced bladder cancer, which is in line with the result from prognosis nomogram chart." (PMID 37197716, 2023). "Tumors from female-gender bladder cancer patients have high mRNA expression of PPARG and a higher level of PPARG receptor expression when compared with their male-gender counterparts." (PMID 37666817, 2023). "Taken together, these analyses support the validity of the screen, and provided a list of potential regulators of PPARG in bladder cancer." (PMID 37250326, 2023). "Here, we developed an endogenous PPARG reporter system in luminal bladder cancer cells and performed genome-wide CRISPR knockout screening to identify bona fide regulators of PPARG gene expression." (PMID 37250326, 2023). "We therefore sought to identify putative regulators of PPARG mRNA expression by performing a genome-wide CRISPR knockout screen in a luminal bladder cancer reporter cell line." (PMID 37250326, 2023). "These aspects are fundamental to cancer development and progression, and thus, unraveling the regulatory mechanisms that control PPARG gene expression in bladder cancer has important implications for the understanding and treatment of the disease." (PMID 37250326, 2023). "Overall, we have generated a reporter system to monitor changes in PPARG gene expression in bladder cancer cells." (PMID 37250326, 2023). "Correlation of our hits with PPARG in MIBC samples was used as a first means to filter our screen results to include those with likely relevance to bladder cancer in vivo." (PMID 37250326, 2023). "We performed a genome-wide CRISPR screen to identity endogenous regulators of PPARG gene expression in bladder cancer." (PMID 37250326, 2023).